HRAS (HRas proto-oncogene, GTPase)
Diseases named in the same sentence as HRAS in open-access papers (continued):
Sharing a sentence is not in itself a finding about the gene and the disease.
pancreatic cancer (29 papers, 1996 to 2025). "RAS (KRAS, NRAS, and HRAS) is the most frequently mutated gene family in cancers, especially lung, colorectal, and pancreatic cancers." (PMID 36817861, 2023). "Why is KRAS preferentially mutated in pancreatic cancer and why does this member of Ras have the highest overall mutagenic propensities relative to the other two, closely related Ras members, HRAS and NRAS?" (PMID 25265995, 2014). "The RAS protein family—KRAS, NRAS, and HRAS—consists of small GTPases, with KRAS mutations detected in 86–91% of pancreatic cancer cases." (PMID 39770538, 2024). "Why KRAS mutations prevail in colorectal, lung and pancreatic cancer, while NRAS or BRAF are mutated more frequently in skin melanoma, and HRAS mutations are predominant in head and neck squamous cell carcinoma is not yet clear." (PMID 28152508, 2017). "The same C118S mutation engineered into HRAS and NRAS was previously shown to reduce the tumor growth of the KRAS mutation-positive human pancreatic cancer cell line CFPac-1." (PMID 25902334, 2015). "In a recent analysis of 2,400 pancreatic cancer patients of whom 82% were found to have mutated KRAS, mutations in BRAF, EGFR, HER2, FLT3, HRAS, PDGFRA, and PTEN were identified exclusively in KRAS wild-type patients, and even there, only rarely (8%)." (PMID 26161408, 2015). "Mutant KRAS–SOS1–WT RAS allosteric signaling promotes growth of KRAS-mutated pancreatic cancer cell xenografts, but has not been assessed for mutant HRAS- or NRAS-dependent transformation." (PMID 33924994, 2021). "Once again, with more than 94% Pancreatic cancer patients carrying KRAS mutation and RAS genes (KRAS, NRAS, and HRAS) were observed to interact with each other through their mutations status and gene expression, it is highly expected that RAS genes could be highly associated with survival outcome." (PMID 30517129, 2018). "More recently, it was shown that human bladder and pancreatic cancer cells that harbor oncogenic HRAS or KRAS mutations, respectively, display an enhancement of macropinocytosis relative to cancer cells of the same tissue type that express wild-type HRAS or KRAS." (PMID 29085336, 2017). "However, we chose to keep the same predictor tools, i.e., AllergenFP, that we had previously used for experimentally tested in-house data, including pancreatic cancer peptides (HRAS and KRAS) and non-structural COVID." (PMID 36298543, 2022).
head and neck squamous cell carcinoma (25 papers, 2016 to 2025). A squamous cell carcinoma that arises from any of the following anatomic sites: lip and oral cavity, nasal cavity, paranasal sinuses, pharynx, larynx, and salivary glands. "While the majority of oncogenic RAS mutations are in KRAS (commonly found in pancreas, lung, and colon carcinomas), bladder urothelial carcinomas, head and neck squamous cell carcinomas, and rhabdomyosarcomas more frequently harbor HRAS mutations." (PMID 40634537, 2025). "Tipifarnib treatment against HRAS-mutant head and neck squamous cell carcinomas described an ideal overall response rate and survival benefit HNSCCC patients with metastatic HRAS mutations." (PMID 37903125, 2023). "A study of tipifarnib in HRAS-mutant specific models demonstrated that tipifarnib inhibits tumor growth in patient-derived xenograft (PDX) models of head and neck squamous cell carcinoma (HNSCC) and transgenic murine models of thyroid cancer." (PMID 35459782, 2022). "For example, CPSF1 promotes head and neck squamous cell carcinoma growth by regulating AS in cancer-associated genes, such as AKT2, HRAS, TGFBI, and UBE2C." (PMID 33748106, 2021). "Although the FDA rejected its approval for acute myeloid leukemia (AML), tipifarnib has shown promise in HRAS-mutant head and neck squamous cell carcinoma (HNSCC) (NCT02383927), and in January 2021, the FDA granted a breakthrough therapy designation (BTD) to Zarnestra." (PMID 40597785, 2025). "We first investigated sotorasib, which is already approved for clinical treatment of KRAS-G12C lung adenocarcinoma, in combination with tipifarnib, an FTi that was recently granted Breakthrough Therapy Designation for treatment of HRAS mutant head and neck squamous cell carcinoma." (PMID 38278976, 2024). "Tipifarnib, a farnesyl transferase inhibitor (FTI), is a small molecule drug that has demonstrated encouraging clinical activity in a genetically-defined subset of head and neck squamous cell carcinoma (HNSCC)–specifically, tumors that express a mutation in the HRAS protooncogene." (PMID 34771475, 2021). "Responses to the FTI tipifarnib were reported in patient-derived models of HRAS-mutant head and neck squamous cell carcinoma (HNSCC) and NSCLC." (PMID 39337337, 2024). "Tipifarnib is the only targeted therapy breakthrough for HRAS-mutant (HRASmt) recurrent or metastatic head and neck squamous cell carcinoma (HNSCC)." (PMID 38672653, 2024). "Tipifarnib, a farnesyl transferase inhibitor, is a small molecule drug candidate that has demonstrated promising clinical activity in HRAS-mutant head and neck squamous cell carcinoma (HNSCC)." (PMID 34771475, 2021). "Tipifarnib is currently under clinical development for treatment of HRAS-mutant thyroid cancer, head and neck squamous cell carcinoma (HNSCC), and non-small-cell lung carcinoma (NSCLC)." (PMID 34830024, 2021). "Simultaneously, in the Cancer Genome Atlas (TCGA) database, a subgroup of head and neck squamous cell carcinoma (HNSC, samples = 508) patients with favorable clinical outcomes showed infrequent copy number alterations that were correlated with activating mutations of HRAS, RAF, RAC1, and ERK1/2." (PMID 32419796, 2020).
head and neck squamous cell carcinoma (continued). "Gal1 increases H-Ras-driven MAPK output, and its elevated expression correlates with poorer survival in HRAS mutant cancers, such as head and neck squamous cell carcinoma, which frequently displays elevated Gal1 levels." (PMID 38982284, 2024).
head and neck cancer (24 papers, 2015 to 2025). A primary or metastatic malignant neoplasm affecting the head and neck. "Lastly, HRAS mutations were generally rare but relatively frequent in bladder/urinary tract cancers and head and neck cancers." (PMID 40970755, 2025). "In this study, we evaluated the frequency of HRAS mutations in head and neck carcinomas and characterized the clinical and cell biological features of carcinomas with HRAS mutations." (PMID 40243851, 2025). "Both mechanistic and genetic evidence suggest that Gal1 acts as a positive modifier that is associated with a worse progression of HRAS mutant cancers, notably head and neck cancers that are frequently associated with high Gal1 levels." (PMID 38982284, 2024). "HRAS mutation has been frequently noted in head and neck cancers; however, the mechanism of HRAS mutation involved in the initiation of oral squamous cell carcinoma (OSCC) still remains unexplored." (PMID 37868370, 2023). "For example, KRAS is most commonly mutated in the Ras family in pancreas (60–90%), colorectal (30–50%), and lung (15–30%) adenocarcinomas, while NRAS has the highest mutation rate in melanoma (15–30%) and HRAS in head and neck cancer (6%)." (PMID 32524209, 2020). "Tipifarnib, a farnesyltransferase inhibitor (FTI) affecting the post-translational modification of HRAS to prevent membrane binding, demonstrated clinical activity in an open-label Phase-II study of patients with HRAS-mutated (HRASmt) head and neck cancer, with an objective response rate of 55%." (PMID 38672653, 2024). "For example, HRAS mutations were identified in a subset of patients with head and neck cancers, suggesting that use of downstream ERK or MEK inhibitors may be of benefit." (PMID 26015395, 2015). "HRAS mutations have the ability to trigger YAP1-AXL signaling, leading to metastasis in head and neck cancer." (PMID 38933262, 2024). "HRAS mutations are comparatively less frequent than KRAS and NRAS mutations but in head and neck cancers, HRAS mutations are most frequently detected." (PMID 37868370, 2023). "HRAS is a member of the RAS oncogene family, and its mutations are common in a variety of cancers, including head and neck cancer, skin cancer, and hematopoietic cancers." (PMID 34580608, 2021). "Of note, FTis are only in clinical phase II trials for HRAS mutant head and neck cancers (clinicaltrials.gov ID: NCT03496766; NCT02383927; NCT03719690) and are not clinically approved for other diseases in contrast to statins and N-bisphosphonates." (PMID 32524209, 2020). "Activating mutations in one of the three RAS genes (HRAS, KRAS, and NRAS) are observed in 5–10% of patients with head and neck cancer, and HRAS mutations in particular are detected in > 50% of patients with head and neck cancer." (PMID 29374236, 2018). "Furthermore, addition of Ras-effector inhibitor therapies are believed to enhance the effects of tipifarnib, through reduction of compensatory MAPK/PI3K pathway signalling potentially brought about by HRAS inhibition in head and neck cancer cell lines." (PMID 39372214, 2024). "However, other mutations, such as Notch1, CDKN2A, FAT1, PTEN HRAS, and PI3KCA, frequently occurring in head and neck cancer, may influence metastatic events." (PMID 37894373, 2023). "Moreover, according to a curated set of non-redundant studies in cBioPortal, CASP8 and HRAS mutations, they seem to be generally more frequent in head and neck cancers (9.57% and 5.83%, respectively) than in gastroesophageal adenocarcinomas and squamous cell carcinomas (2.07% and 0.15%)." (PMID 35664801, 2022). "We confirmed previous observations that laryngeal and pharyngeal cancers rarely harbor CASP8 and HRAS mutations in comparison to oral cancers – in our comparison, these alterations were almost completely absent in hypopharyngeal tumors when juxtaposed with other head and neck cancer subtypes." (PMID 35664801, 2022).
head and neck cancer (continued). "Recently, interest has been renewed towards FTis for the treatment of HRAS mutant solid tumors with encouraging results in phase II trials, leading to FDA approval for HRAS mutant head and neck cancer, and for the Hutchinson-Gilford progeria syndrome, where the target is progerin." (PMID 38278976, 2024).
colon carcinoma (23 papers, 2008 to 2025). "The three human RAS genes (KRAS, NRAS and HRAS) are the most frequently mutated oncogenes in human cancer appearing in 90% of pancreatic, 35% of lung and in 45% of colon cancers." (PMID 29534749, 2018). "Meanwhile, knockdown of WDR76 enhances the resistance of 5-FU in colon cancer both in vitro and vivo, which was reversed by a specific inhibitor of HRAS, Kobe006." (PMID 37081180, 2023). "In particular, KRAS is the isoform prevalently mutated in pancreas, lung and colon cancer, while NRAS is the predominant isoform mutated in cutaneous melanomas and acute myelogenous leukemia and HRAS is the predominant isoform mutated in the bladder." (PMID 29534749, 2018). "Our study indicated that WDR76/HRAS axis could reversely manipulate the sensitive of resistant colon cancer cells to 5-FU." (PMID 37081180, 2023). "The WDR76/HRAS axis might serve as an effective target of 5-FU resistance in colon cancer." (PMID 37081180, 2023). "HRAS, a member of RAS protein family, has not been reported in 5-FU resistant colon cancer." (PMID 37081180, 2023).
squamous cell carcinoma (23 papers, 1993 to 2025). A carcinoma arising from squamous epithelial cells. "The migration of squamous cell carcinoma cells with an HRAS mutation was attenuated by the inhibition of HRAS protein expression, whereas those without an HRAS mutation were not affected." (PMID 40243851, 2025). "HRAS is the predominant mutated RAS isoform in several types of squamous cell carcinomas, including HNSCCs." (PMID 40243851, 2025). "A review summarized potential mechanisms by which BRAF inhibitors can induce squamous cell carcinoma, including individual HRAS gene mutations and infections with human papillomavirus (HPV) or human polyomavirus (HPyV)." (PMID 40231257, 2025). "For a proof-of-concept, we designed epitope-based vaccine candidates for squamous cell carcinoma, selected from the top mutated epitopes of the HRAS gene." (PMID 35062725, 2021). "In squamous cell carcinoma, HRAS activation leads to layering via the loss of tissue polarity and organization." (PMID 34644109, 2021). "In addition, we analyzed the underlying biological mechanisms related to prognosis and distant metastasis, which were likely to be associated with HRAS mutations, in terms of migration ability and cytotoxicity using squamous cell carcinoma cell lines." (PMID 40243851, 2025). "Interestingly, HRAS was the most commonly mutated RAS GTPase in both squamous cell carcinoma and transitional cell carcinoma." (PMID 34645806, 2021). "Alternatively, this may suggest a role for the immune response in the development of secondary squamous cell carcinomas in light of the possible etiologies of their development via HRAS mutations in keratinocytes." (PMID 27532019, 2016). "Thus, we might have missed other HRAS-mutant tumours, since HRAS mutations were also rarely described in squamous cell carcinoma." (PMID 35621690, 2022). "These included 12 adenocarcinomas, 9 squamous cell carcinomas and 1 large cell carcinoma, all examined for known EGFR/KRAS/NRAS/HRAS/PI3K mutations." (PMID 19806209, 2009). "However, PCOptim-CD was not as effective in our vaccine design as compared to other datasets—when PCOptim-CD was used on epitope data for a vaccine design targeting the HRAS gene for squamous cell carcinoma, the optimized dataset contained six epitopes." (PMID 37513844, 2023). "Although the higher relative level of HRAS gene expression was observed in the group of patients with squamous cell carcinoma subtypes of NSCLC (N = 23) than in the group with adenocarcinoma (N = 16), this difference was not statistically significant (p = 0.065)." (PMID 33549031, 2021). "Some of the most important observations from the presented work were that overexpression of HRAS gene in blood had occurred more frequently in smokers and there was a tendency to the higher expression of the HRAS gene in patients with squamous cell carcinoma subtypes of NSCLC." (PMID 33549031, 2021). "A significant inhibitory effect of HRAS knockdown on cell migration was observed in HRAS mutation-positive cells, but not in HRAS mutation-negative cells, suggesting that mutation-positive HRAS plays a pivotal role in the migration of squamous carcinoma cells, resulting in distant metastasis." (PMID 40243851, 2025). "Similarly, in skin cancer the wild-type HRAS allele decreased the number of HRAS mutated papillomas but not the number of squamous cell carcinomas." (PMID 36607281, 2023). "Interestingly, the relative level of HRAS gene expression in blood was shown to be higher in the squamous cell carcinoma than in glandular subtypes, indicating that HRAS gene expression may be regulated developmentally and differentially." (PMID 33549031, 2021).
squamous cell carcinoma (continued). "Patients with squamous cell carcinoma subtypes of NSCLC were more likely to show an overexpression of HRAS gene in blood, but not statistically significant (p = 0.065)." (PMID 33549031, 2021).
Noonan syndrome (21 papers, 2010 to 2026). Noonan Syndrome (NS) is characterized by short stature, typical facial dysmorphism and congenital heart defects. "Somatic pathogenic variants in genes of the RAS/MAPK signaling pathway, in turn, are causative for RASopathies such as Noonan syndrome (BRAF, MAP2K1, PTPN11, or RAF1 variants), Costello syndrome (HRAS variants) as well as other Noonan-like syndromes." (PMID 38835734, 2023). "There are mutations at components of the Ras/Raf/MEK/ERK pathway in the related Costello and Noonan syndromes, including: SOS, and PTPN11 (Shp2) in Noonan syndrome and HRAS mutations in Costello syndrome." (PMID 21422497, 2011). "RAS paralogs (HRAS, NRAS and KRAS) are of major interest in biology because they are involved in developmental disorders (e.g., Costello and Noonan syndromes) and in a broad variety of human neoplasia." (PMID 33187149, 2020).
sarcoma (19 papers, 2012 to 2025). A usually aggressive malignant neoplasm of the soft tissue or bone. "HRAS belongs to the Ras oncogene family, whose members are associated with mammalian sarcoma retroviruses." (PMID 36772869, 2023). "KRAS and HRAS were initially identified in cancer cells as the human orthologs of those proto-oncogenes responsible for the initiation of sarcoma in rats infected with two cancer-causing viruses, while NRAS was discovered shortly after by homology with KRAS and HRAS." (PMID 35234863, 2022). "As a member of the RAS oncogene family, HRAS is in relation to the transforming genes of mammalian sarcoma retroviruses." (PMID 35387180, 2022). "The rat sarcoma (RAS) genes, including HRAS, KRAS, and NRAS, encode a family of proteins regulating cell growth, differentiation, and apoptosis." (PMID 24782938, 2014). "The Harvey (HMSV) and Kirsten (KMSV) murine sarcoma RNA tumor viruses, named HRAS and KRAS after their respective discoverers, were shown to induce sarcoma and erythroleukemia in rats in the 1960s." (PMID 22928112, 2012). "HRAS and HRas or H-Ras—human species: Harvey rat sarcoma[virus] gene and protein, respectively." (PMID 40906088, 2025). "Thus, repression of HRAS following CDK4 inhibition was not specific to sarcoma cell lines." (PMID 28855512, 2017).